CXCR1 (C-X-C motif chemokine receptor 1)
Diseases named in the same sentence as CXCR1 in open-access papers (continued):
Sharing a sentence is not in itself a finding about the gene and the disease.
tumor (continued). "Moreover, inhibition of CXCR1/2 signalling impaired the proliferative capacity of irradiated PC3 tumours as shown by reduction in the Ki-67 positive cell population." (PMID 32743555, 2020). "Interestingly, CXCR1/2 inhibition reversed the chemoresistance induced by MSCs, as tumor progression was abolished when mice were treated with a mix of carboplatin and CXCR1/2 inhibitor (reparixin)." (PMID 31504643, 2020). "Finally, when SKOV-3 + MSC tumor-bearing mice were treated with reparixin, we observed a decrease in the levels of peritoneal CXCR1/2 ligands, suggesting that a CXCR1/2 blockade leads to a decrease in the expression of its ligands." (PMID 31504643, 2020). "We then demonstrate the plasticity of this phenotype in vivo and ex vivo by re-sensitizing the tumor cells to chemotherapy using CXCR1/2 receptor inhibitors, which may be a promising therapeutic strategy to circumvent resistances in patients." (PMID 31504643, 2020). "Previous studies have shown that CXCRs are expressed at high levels in a variety of tumor tissues, but this study has, for the first time, summarized the expression of CXCR1-7 in ccRCC." (PMID 33324682, 2020). "Activation of the CXCR1/CXCR2 pathway and the CXCR4/CXCR7 pathway is associated with tumor aggressiveness and poor prognosis; the CXCR3 and CXCR5 axes play a role in tumor suppression; and common variants encoding the CXC chemokine gene have also been studied as biomarkers of CRC." (PMID 32774427, 2020). "For instance, CXCR1+ cells formed 19.3% of the dissociated tumor cells derived from Caki‐1 sphere xenografts in first round of transplants, and that proportion increased to 23.4% in the second round, and finally reached 34.4% in the third round of transplantation." (PMID 30883740, 2019). "CXCR1 and CXCR2 have been linked to melanoma tumor growth and metastasis." (PMID 30873179, 2019). "We hypothesized that co-expression of the IL-8 chemokine receptors CXCR1 or CXCR2 would enhance CAR T-cell migration towards tumor cells and thereby further improve therapeutic activity." (PMID 31091832, 2019). "In search of novel renal CSC markers, we identify an essential role for IL‐8 (CXCL8)/CXCR1 signaling in proliferation, migration, invasion, sphere formation and self‐renewal capabilities of ccRCC‐derived tumor cells, suggesting a stemness signature of this cell population." (PMID 30883740, 2019). "Interestingly, high IL‐8 and CXCR1 levels were found in the xenograft tumor tissue derived from spheres as well as elevated IL‐8 concentrations in serum of these xenografts." (PMID 30883740, 2019). "Moreover, using mutants and pharmacological inhibition, we show that the chemokine receptor Cxcr1 promotes neutrophil recruitment, proliferation of tumor-initiating cells, and neoplastic mass formation." (PMID 30185911, 2018). "Therefore, we characterized the role of the IL-8 receptor Cxcr1 in regulating neutrophil recruitment to tumor-initiating cells." (PMID 30185911, 2018). "Accordingly, the tumor volume was smaller in the CXCR1 knockdown group than in the control." (PMID 29915309, 2018). "CXCR1 has also been involved in tumor metastasis, as it binds CXCL6 and CXCL8." (PMID 30591657, 2018). "The two receptors are expressed not only on leukocytes and tumor cells but also on neutrophils, monocytes, macrophages, basophils, natural killer T-cells and others normal cells; in addition, a lower percentage of T-cells express CXCR1/2." (PMID 30123110, 2018). "There is a broad prospect for the study of CXCR1, which might become an effective target for anti-tumor therapy." (PMID 28454081, 2017). "In particular, the obtained data suggest that the inhibition of CXCR1/2 combined with standard taxane therapy, in addition to potentiating the taxane anti-tumor activity can reduce chemotherapy-induced neurotoxicity, thus giving some insight for the development of novel treatments." (PMID 28423567, 2017).
tumor (continued). "Further association between the CXCL1/CXCR1 gradient and patient outcome was obtained from our analysis of the tissue microarray: high epithelial CXCL1 and high stromal CXCR1 expression was observed for 100% of analysed tumours from patients who eventually deceased." (PMID 27241286, 2016). "Several studies have suggested that CXCR1 is an important player in tumor progression." (PMID 27682863, 2016). "Additionally, CXCR1 blockade in vivo decreased metastasis formation, and combination with docetaxel or paclitaxel reduced primary tumor growth or brain metastases, respectively, better than either agent alone." (PMID 27348007, 2016). "Recently, we reported that TAM in PTC facilitated tumor metastasis through releasing CXCL8 and may target CXCR1/2 in tumor cells." (PMID 26875556, 2016). "In addition, such enhancements were accompanied by an overexpression of CXCL8/CXCR1, whose role in tumor angiogenesis and progression has been demonstrated." (PMID 26696754, 2015). "The current bulk of available data clearly outlines that IL-8, expressed by tumour cells and induced by chemotherapeutic treatment, is a key regulator of the survival and self-renewal of the small population of CXCR1-expressing CSC, thus setting the premises for important clinical studies." (PMID 26517518, 2015). "Further, the secretion of IL-8 from cancer cells may have a variety of effects on the tumor microenvironment, because the IL-8 receptors CXCR1 and CXCR2 are expressed on cancer cells, endothelial cells, neutrophils and tumor-associated macrophages." (PMID 25694811, 2014). "Furthermore, not only the number of CSCs but also a reduction in general tumor cell viability is achieved by the use of CXCR1 inhibitors." (PMID 25165728, 2014). "Because there are fewer chemokine receptors than chemokine ligands, we first assessed the levels of expression of mRNAs encoding all 18 types of chemokine receptors (CXCR1-6, CCR1-10, XCR1, and CX3CR1) in the inflammatory cells located around the tumor in our patient." (PMID 25123545, 2014). "Moreover, it has been shown that impeding neutrophil recruitment to the tumor site via CXCL8 or CXCR1/2 inhibition can reduce tumor growth in vivo." (PMID 24276377, 2013). "CXCR1/2-targeted therapies may therefore reduce intratumoral neutrophils, thereby impeding tumor progression facilitated by neutrophil infiltration." (PMID 24276377, 2013). "Besides tumor cells, IL-8 and its receptors CXCR1 and CXCR2 have been observed on endothelial cells and have been shown to play a role in endothelial cell proliferation." (PMID 22507529, 2012). "In addition, levels of CXCR1 were also found to be significantly reduced in NSCLC tumours (35.2%, p<0.05)." (PMID 21298036, 2011). "An IL-8 homologue is absent from the mouse genome and these precludes incisivedefinitive genetic experimentation on the role of IL-8 in murine tumor models.However there are reports suggesting that mouse CXCR1 is activated by human IL-8,hence permitting to some extent experiments in xenografts." (PMID 21423807, 2011). "Several studies have implicated CXCR1 and CXCR2 as important players in tumour progression." (PMID 19401689, 2009). "Moreover, CXCR1 and CXCR2 are implicated in tumour growth by directly enhancing tumour cell properties, thus indicating the possibility of manipulating CXCR1 and CXCR2 for future therapeutic intervention." (PMID 19401689, 2009). "Interestingly, both the lL‐8 neutralizing antibody and the CXCR1/2 inhibitor could hinder tumor sphere formation induced by TRAF4 nuclear accumulation." (PMID 39716976, 2025). "Furthermore, IL-8 in the FME may subsequently trigger cancer cells to generate more IL-8, which reacts with CXCR1 on the tumor cell surface in a positive feedback loop, leading to cancer progression through such a vicious cycle." (PMID 38891100, 2024).
tumor (continued). "Organoids, 3D cultures derived either from PCa cell lines or patient tumours that maintain the genetic and phenotypic characteristics of the original tumour, may offer a promising platform for drug screening and understanding IL-8/CXCR1/2 tumour-intrinsic and TME biology in a controlled environment." (PMID 39199570, 2024). "Thus, combination therapy, such as radiotherapy plus SX-682 (CXCR1/2 inhibitor), could abrogate the recruitment of tumor MDSCs and enhance the tumor infiltration and therapeutic efficacy of NK cells." (PMID 38264648, 2023). "The CXCR2-ADRA1A function module generated from our data included several immune-related genes, such as CXCL5, CXCL13, RGS12, and CXCR1, indicating that the DNA methylation function module might involve in the immune response regulation in the tumor microenvironment of sMPLC." (PMID 36611170, 2023). "The ensuing migration of monocytes/macrophages and myeloid cells via CXCR1/2-mediated chemotaxis into the TME subsequently promotes tumour progression, whether that be through initiating NFKB pro-survival signalling in tumour cells or by facilitating their escape from senescence." (PMID 34128831, 2021). "Moreover, tumor development may occur via IL-8-initiated activation of CXCR1/2 signaling, leading to activation of NF-κB, which in turn promotes further tumor development." (PMID 33466795, 2021). "Additionally, antagonism of CXCR2 (danirixin) could promote tumor progression more effectively than CXCR1/2 (reparixin) in CT26 tumor model." (PMID 34025668, 2021). "Moreover, IL‐6 induced CD4+Foxp3+ Treg migration into tumor sites by upregulating CXCR1 expression." (PMID 32931642, 2020). "However, CXCR1 does not seem to be directly associated with vascular invasion, as it was equally expressed in the primary tumour and at the invasion front." (PMID 29976164, 2018). "Moreover, such an autocrine forward-feedback loop can also be diminished by IL-8 neutralizing antibody or blockade of IL-8 receptors CXCR1/2 with reparixin, and, in a human xenograft model, administration of reparixin after chemotherapy withdrawal effectively attenuates tumor masses." (PMID 30175384, 2018). "However, chemokine gradients could conceivably facilitate adhesion of tumor cells lodged in the tight pulmonary arterioles and capillaries to the CXCR1‐expressing pulmonary endothelium." (PMID 28341702, 2017). "We cross‐examined the genotype of various tumor cells with their ability for automatic pulmonary dissemination, modulated NRAS expression using RNA interference and NRAS overexpression, identified NRAS signaling partners by microarray, and validated them using Cxcr1‐ and Cxcr2‐deficient mice." (PMID 28341702, 2017). "Hence, CXCR1/2 inhibitors could inadvertently promote tumor growth by blocking the anti-tumor effects of neutrophil infiltration." (PMID 27019857, 2016). "Our data indicate that CXCR1 signalling induces α-smooth muscle actin (αSMA) expression in ASCs and their stimulatory effects on endothelial cells, thus suggesting the molecular mechanism through which ASCs are recruited by tumours and promote their vascularization and growth." (PMID 27241286, 2016). "An increased expression of IL-8 and its receptors CXCR1 and CXCR2 has been demonstrated in cancer cells, infiltrating neutrophils, tumor-associated macrophages and endothelial cells, suggesting a function as a regulatory factor within the tumor microenvironment." (PMID 24281035, 2010). "Further analysis revealed a positive correlation between CXCL8 expression in pMQs and its receptors, CXCR1 and CXCR2, in matched tumor cells." (PMID 39937005, 2025). "Taken together, DDX17 promoted tumor growth and facilitated HCC metastasis, whereas the CXCR1/2 inhibitor, Reparixin, reversed the oncogenic effect of DDX17 in HCC progression." (PMID 39897048, 2025). "Enhanced tumor-homing abilities and anti-cancer effectiveness have been demonstrated in CAR-T cells expressing CXCR1, CXCR2, or integrin αvβ6." (PMID 40382583, 2025).
tumor (continued). "Pembrolizumab is an anti-PD-1 antibody, and the treatment aimed to simultaneously block CXCR1/CXCR2 signaling and a key immune checkpoint involved in tumor immune evasion." (PMID 40427171, 2025). "Glutamic acid-leucine-arginine positive (ELR+) CXC chemokines and their receptors, CXC chemokine receptor 1 and 2 (CXCR1 and CXCR2), mediate both inflammatory responses and tumor progression." (PMID 41425704, 2025). "Tumor-associated neutrophils (TANs) are pivotal immune cells that populate the tumor microenvironment (TME) and can be drawn in by IL-8 through CXCR1/CXCR2 signaling." (PMID 40281554, 2025). "Tumor cells secrete multiple inflammatory chemokines, primarily mediating neutrophil migration to tumors via CXC chemokines such as CXCR1 and/or CXCR2." (PMID 40963981, 2025). "A recent study revealed that concurrent inhibition of PD-L1, CXCR1/2, and TGF-β significantly augmented T-cell infiltration and activation in the tumor microenvironment, consequently enhancing the antitumor activity of ICI." (PMID 40013144, 2025). "Several groups have sought to target this by armoring CAR T-cells with CXCR1 or CXCR2, both of which are CXCL8 receptors, with the aim of exploiting tumor CXCL8 expression to improve CAR T-cell migration to tumors." (PMID 41019052, 2025). "CXCR1/CXCR2-armoring has been demonstrated to improve CAR T-cell infiltration, persistence, and tumor control in vivo across several studies." (PMID 41019052, 2025). "Chemokines entered the bloodstream, which interacted with CXCR-1 and CXCR-2 (G protein-coupled receptors) on neutrophils and facilitated their directed movement toward tumor sites." (PMID 40697377, 2025). "For instance, Vδ2+ T cells primarily migrate through CCR5-mediated chemotaxis, whereas Vδ1+ T cells predominantly rely on CXCR1 and CXCR3, leading to differentiated tissue migration and tumor infiltration patterns." (PMID 40141420, 2025). "OC cells expressing the C-X-C motif chemokine receptor 1 (CXCR1) are attracted by IL-6, IL-8, monocyte chemoattractant protein-1, and tissue inhibitor of metalloproteinases-1 secreted by the omentum during tumor dissemination." (PMID 39964754, 2025). "In a PDAC murine model, the KRAS G12D reversible inhibitor, MRTX1133, when combined with CXCR1/2 inhibitor and anti-LAG3 and anti-41BB antibodies yielded complete tumor regression and prolonged survival in 36% of mice at 6 months." (PMID 40227779, 2025). "Research has shown that chemokine receptor agonists CXCR1 and CXCR2, produced by tumor cells, induce the formation of NETs, which act as a shield protecting tumor cells against cytotoxicity mediated by natural killer (NK) cells and T cells." (PMID 40801632, 2025). "In this review we described the significance of CXCR1, CXCR2 and CXCR3 receptors and their ligands in tumor processes in MM and MGUS." (PMID 40940985, 2025). "Their trafficking and infiltration into solid tumors is frequently suboptimal, although this can be improved by engineering expression of chemokine receptors such as CXCR4, CXCR1, or CXCR2 to match tumor-secreted ligands." (PMID 40941014, 2025). "Key chemokines involved in this process include CXCL1, CXCL2, and CXCL8 (IL-8), which bind to the CXCR1 and CXCR2 receptors on neutrophils, guiding them to the tumor site." (PMID 41180630, 2025). "For example, CAR-T cells engineered to express chemokine receptors such as CXCR1, CXCR2, or CCR2 demonstrate enhanced migration toward tumor sites that secrete corresponding chemokines, such as CXCL8 for CXCR1/2 and CCL2 for CCR2." (PMID 41584600, 2025). "The results showed that CXCL8, through binding to CXCR1/2, activates the PI3K/AKT and MAPK signaling pathways, enhancing the migration and invasion capabilities of tumor cells." (PMID 40573881, 2025).
tumor (continued). "The co-expression of CXCR1 and a CAR resulted in enhanced migration towards the pro-inflammatory cytokine IL-8 gradient, leading to increased infiltration and anti-tumour response in mice carrying established peritoneal ovarian cancer xenografts." (PMID 40650066, 2025). "CXCR1 and CXCR2 inhibitors, including reparixin, have been evaluated in early clinical trials with the intent of disrupting IL-8-driven tumor biology." (PMID 41007766, 2025). "CD36 displayed strong positive correlations with immune receptors such as CCR1, CCR2, CCR4, CXCR1, and CXCR2, indicating its potential role in amplifying chemokine-receptor interactions and shaping immune cell trafficking within the tumor microenvironment." (PMID 41550652, 2025). "CXCL8 recruitment and activation of neutrophils by binding to CXCR1 and CXCR2 has been shown to enhance tumor growth and proliferation through secretion of a variety of cytokines and angiogenic factor release." (PMID 41376630, 2025). "Chemokine receptor engineering (CXCR1, CXCR4, CCR7) improves trafficking and tumor infiltration both in hematological and solid tumors." (PMID 41487532, 2025). "Combining CDK4/6 and CDK2 inhibitors with the CXCR1/2 antagonist, SX-682, halted B16F10 tumor growth by blocking tumor cell proliferation and increasing the anti-tumor immune response in the tumor microenvironment." (PMID 40904502, 2025). "By inhibiting the binding of CXCL8 and CXCR1/2, the aggregation of immunosuppressive cells (e.g., neutrophils, TAMs, etc.)in the TME can be reduced, thereby promoting the anti-tumor activity of effector T cells." (PMID 41376630, 2025). "For example, CXCR1 and CXCR2 are known to facilitate the recruitment of neutrophils to tumor sites, promoting tumor cell proliferation and angiogenesis, both of which are crucial for tumor growth and metastasis." (PMID 41024311, 2025). "Nevertheless, interleukin-8, also known as CXCL8, binds to the receptors CXCR1 and CXCR2 has been shown to mediate tumour progression, epithelial-mesenchymal transition, invasion, and angiogenesis." (PMID 40852716, 2025). "CXCR1 and PTGS2 genes had significantly higher expression in patients with N1 metastasis, whereas VEGFB expression was significantly higher in tumour samples with N3 metastasis." (PMID 38426619, 2024). "Significant upregulation of PTGS2, VEGFA, KDR, CXCR1, and CXCR2 expression were observed in tumour samples compared with paired normal samples." (PMID 38426619, 2024). "IL-8 exerts its biological effects primarily through binding to its cognate receptors, CXCR1 and CXCR2, which are expressed on the surface of various cell types, including cancer cells and cells within the tumor microenvironment." (PMID 38891100, 2024). "The study revealed that CA-MSCs highly express CXCR1/2 ligands such as CXCL1, CXCL2, and IL-8, which promote monocyte differentiation towards a pro-tumor M2 phenotype, facilitating tumor progression and the acquisition of chemotherapy resistance." (PMID 38779660, 2024). "Owing to their role in promoting angiogenesis, CXCR1 and CXCR2 have been correlated with the development, invasion and metastasis of OSCC tumours." (PMID 38426619, 2024). "In our study, we found that PTGS2 and VEGF signalling pathway genes (VEGFA, VEGFB, KDR, CXCR1 and CXCR2) were upregulated in OSCC tumour tissues compared to their paired normal tissues." (PMID 38426619, 2024). "In this study, a significant increase in PTGS2 with VEGFA, KDR, CXCR1 and CXCR2 expression was observed in tumour samples compared to their paired normal samples, with the exception of VEGFB, whose expression was not statistically significant." (PMID 38426619, 2024). "Based on the results obtained, PTGS2, VEGFA, KDR, CXCR1 and CXCR2 were found to be significantly overexpressed in tumour samples compared to paired normal samples." (PMID 38426619, 2024).